CD24 (CD24 molecule)
Diseases named in the same sentence as CD24 in open-access papers (continued):
Sharing a sentence is not in itself a finding about the gene and the disease.
breast cancer (continued). "Therefore, CD24+CD90+ cells from MMTV-PyMT breast cancers, as well as CD24+CD90+ cells from FVB normal mammary gland, were grown in a soft agar matrix." (PMID 27542270, 2016). "CD24 expression has been shown to be upregulated during tumorigenesis in gastric, colon and breast cancer patients, suggesting that besides its role in tumor progression and metastasis, CD24 may also play a role in early tumor development." (PMID 26978528, 2016). "Taken all together, our results here indicate that cell surface expression of CD24 in breast tumor cells may serve as a valuable biomarker to identify breast cancer patients that will benefit from anti-IGF1R therapy." (PMID 27179633, 2016). "Furthermore, it was shown that CD24 can serve as an important indicator for poor prognosis for many of the most common malignancies including breast cancer." (PMID 27179633, 2016). "The existence of CSCs in breast cancer was first brought to light when it was found that the CD44+CD24−/lowLin− cells from breast cancer patients were able to generate tumors more efficiently than CD44+CD24+Lin− cells when implanted into the mammary fat pads of NOD/SCID mice." (PMID 27229859, 2016). "Hence, to further investigate this, we determined CD24 cell surface expression in the mammary carcinoma MCF7 cell line." (PMID 27179633, 2016). "Notably, high CD24 expression was more frequently found in HER2-positive breast cancer than in HER2-negative tumours." (PMID 26444008, 2015). "CD24 mRNA expression is downregulated by oestrogen in breast cancer cells." (PMID 26444008, 2015). "It shows that highly aggressive basal-type breast cancer cell lines are characterized by both the high expressions of mesenchymal markers including TGFB1 and the markers associated with cancer stem-like features (CD44+/CD24−)." (PMID 26462028, 2015). "Involvement of CSCs in tamoxifen resistance of breast cancer cells has been reported, which appears to be mechanistically linked with higher expression of CXCR4, STAT3, Sox2, EZH2, and lower expression of CD24." (PMID 26206152, 2015). "The association of CD24 expression with patient survival for different subtypes of breast cancer in our study suggests that targeting CD24 may confer a clinical benefit in patients with the HER2 or TNBC subtype." (PMID 26444008, 2015). "Our results suggest that CD24 overexpression is an independent unfavourable prognostic factor in breast cancer, especially for luminal A and TNBC subtypes, and CD24 may be a promising therapeutic target for specific subtypes of breast cancer." (PMID 26444008, 2015). "nCaPCMHA-AF488 was taken up by CD44+/CD24− BT-474EMT breast cancer cells within 18 hours." (PMID 26448751, 2015). "In the present study, we assessed the prognostic significance of CD24 expression in subgroups of breast cancer including the molecular subtypes to identify patients who could benefit from a therapy targeting CD24." (PMID 26444008, 2015). "The transcript level of CD24 in breast cancer stem cells was observed to be downregulated by Twist." (PMID 26444008, 2015). "CD24 is associated with unfavourable prognoses in various cancers, but the prevalence of CD24 expression and its influence on clinical outcome in subtypes of breast cancers remain unclear." (PMID 26444008, 2015). "Confocal imaging revealed an enhanced membrane expression of CD44 and CD24 in the DTCs derived from the basal-like breast cancer cell line MDA-MB-468 as compared with treatment-naive parent cells, which was validated using fluorescence-activated cell sorting (FACS)." (PMID 25669750, 2015). "Flow cytometric analysis of breast cancer spheroids treated with 40 μM 6-shogaol for 18 hours showed that the percentage of cells characterized by CD44+CD24-/low were substantially less in the treated spheroids when compared to the untreated ones (2.3% vs. 27.3%)." (PMID 26355461, 2015). "Currently, CD24 expression is a new prognostic marker in breast cancer." (PMID 26608463, 2015).
breast cancer (continued). "First, we determined CD24 expression at the transcript level in five breast cancer cell lines representing the subtypes of breast cancer (MCF7 for the luminal A subtype, HCC1419 for the luminal B subtype, SK-BR3 for the HER2 subtype, and MDA-MB–231 and MDA-MB–435 for the TNBC subtype)." (PMID 26444008, 2015). "Additionally, in breast cancer, CD24 was demonstrated to increase the proliferation, motility, and invasiveness of breast cancer cells, in line with its role in promoting tumour growth and metastasis in vivo." (PMID 26444008, 2015). "Tissue CD24 expression levels may help to predict survival in patients with breast cancer, but studies show that highly invasive breast cancer cells often express CD44+/CD24−." (PMID 25511546, 2015). "Moreover, the significant influence of CD24 expression on OS (P = 0.026) was only found in patients with stage I breast cancer." (PMID 26444008, 2015). "Furthermore, the CD44+CD24− phenotype correlated more closely with basal phenotype than with tumorigenicity in breast cancer cell lines." (PMID 25497455, 2015). "CD24 plays a role in facilitating metastasis by the interaction between tumor cells and platelets or endothelial cells and is also associated with proliferation, adhesion and invasion in MCF-7 breast cancer cells affecting their CXCR4 function." (PMID 26405647, 2015). "Aberrant overexpression of CD24 during carcinogenesis and its prognostic significance in multiple types of solid tumours are well known, but the prognostic significance of CD24 expression in different subtypes of breast cancer is unclear." (PMID 26444008, 2015). "Similarly, label-retaining cells (LRC) with self-renewal ability have been identified in a sub-population of CD44+/CD24-/ESA+ breast cancer cells, and these cells were endowed with resistance to chemotherapy." (PMID 26318423, 2015). "Taken together, the present study suggested that the modification of GSN expression might involve in the TGF-β1 signaling events for inducing cancer cell stemness and increasing cell migration and invasion in CD44+/CD24- subpopulation of breast cancer cells." (PMID 26482896, 2015). "Notably, CD24 has also been observed in many human carcinomas, such as ovarian cancer, renal cell cancer, breast cancer and NSCLC." (PMID 26578846, 2015). "In their study, CD24 proved to be necessary for mediation of rolling on P-Selectin, as low expression levels or cleavage of CD24 resulted in inhibition of attachment and rolling, in a breast carcinoma cell line." (PMID 26578846, 2015). "The mammary carcinoma Mvt1 cells were sorted into CD24− and CD24+ cells." (PMID 26040280, 2015). "One study has demonstrated that IMPC may represent a distinct entity of breast carcinoma that exhibits a high expression of CD24 compared with IDC." (PMID 25663874, 2015). "BCSCs were isolated from breast cancer and benign surgical specimens based on CD49f/CD24 markers." (PMID 25269750, 2014). "In the case study presented in this section we attempt to compare the various biological contexts that emerge when examining differentially expressed genes identified from mRNA profiling of CD44+ CD24-/low breast cancer cells as compared with normal breast epithelium tissue." (PMID 24650281, 2014). "In human breast cancer, putative cancer stem cells were first isolated by the expression pattern of cell surface makers, CD44 and CD24, and the breast cancer cells with a CD44+/CD24−/low phenotype were able to form tumors in immunodeficient mice with a very low number of cells." (PMID 25229616, 2014). "However, cancer initiating cells in other neoplasms have been characterized by at least 2 different surface markers; CD44+/CD24-/lin- in breast cancer, a2b5+/CD133- in glioblastoma and CD34+/CD38− in leukemia:." (PMID 25105565, 2014). "Down-regulation of CD24 was observed in CSCs of breast cancer." (PMID 25260650, 2014).
breast cancer (continued). "We investigated in particular whether Alu and LINE-1 hypomethylation is distinct in relation to breast cancer subtype and breast cancer stem cell phenotypes as represented by CD44+/CD24− and ALDH1 expression." (PMID 24971511, 2014). "Many groups have enriched for functional breast cancer stem cells using ESA+/CD44+/CD24−/low." (PMID 24583601, 2014). "Another cell surface marker is the single-chain sialoglycoprotein CD24, which is associated with cancer stem cell characteristics in colorectal and pancreatic cancer, while head and neck cancer cells and breast cancer cells with CD44+CD24−/low expression are highly tumorigenic." (PMID 24122205, 2014). "The data used in this case study for evaluation and validation comes primarily from a study that profiled and compared normal breast epithelium tissue obtained from reduction mammoplasties and highly tumorigenic breast cancer cells isolated from tumors (ESA+ CD44+ CD24-/low Lin-)." (PMID 24650281, 2014). "In breast cancer, these cells were found to be associated with CD44+CD24-low and ALDH+ phenotype." (PMID 23883436, 2013). "CD24 is a cell surface glycoprotein whose level of expression has become commonly used to isolate distinct cell populations from the normal mammary gland and breast cancer cells." (PMID 23986719, 2013). "We found that the CD44+/CD24-/low breast cancer cells showed numerous protrusions on the cell surface and had many microvilli and pseudopodia, indicating such ultrastructures may contribute to higher tumorigenesis and invasion ability." (PMID 23799994, 2013). "It is noteworthy that CD24+ cells are increased in metastatic compared to primary breast cancers." (PMID 23982961, 2013). "Among these cyclohexylmethyl flavonoids, ugonins J and K, which were the main components of the ethyl acetate-soluble extract of the rhizomes of H. zeylanica, were able to suppress propagation of CD24-/lowCD44+ breast cancer stem cells both in vitro and in vivo." (PMID 23662114, 2013). "Their relationship to disseminated tumour cells (DTCs) in tissues is unclear, although a recent publication showed that the presence of CD44+CD24-/lo cells (putative CSCs) in the bone marrow is an independent adverse prognostic indicator in patients with early stage breast cancer." (PMID 24286369, 2013). "Furthermore, we systemically analyzed the ultrasturcture, invasion capacity, and tumor formation in breast cancer MCF7 cells with different CD44/CD24 genotypes." (PMID 23799994, 2013). "Moreover, a positive correlation exists between the expression levels of IL-1alpha, IL-6, IL-8 and the CD44(+)/CD24(-/low) population in breast cancer cell lines." (PMID 24392029, 2013). "Other authors have detected a CD44+/CD24- phenotype in 91.9, 93.0, 76.2, and 44.3% of four different cell lines from canine mammary neoplasms using flow cytometry, however the immunohistochemical expression of these proteins was not demonstrated in canine mammary neoplasms." (PMID 24119896, 2013). "Further, it was found that CD44+/CD24-/low breast cancer cells exhibit epithelial-to-mesenchymal transition (EMT) features that might be responsible for their aggressive clinical behaviour." (PMID 24229464, 2013). "Previous studies support the role of CD24 in breast cancer development." (PMID 23300877, 2012). "Further studies were focused on polo-like kinase 1 (PLK1), including its expression in breast cancer cell lines, effect on the CD44high/CD24-/low TIC subpopulation, growth inhibition, mammosphere formation, and apoptosis, as well as the activity of the PLK1 inhibitor, BI 2536." (PMID 22309939, 2012). "For example, Gupta and colleagues utilized a chemical screen to identify drugs with selective toxicity for BCSCs and found that salinomycin was able to reduce the prevalence of CD44+/CD24− BCSCs compared to paclitaxel, a commonly used breast cancer chemotherapeutic agent." (PMID 24977105, 2012).
breast cancer (continued). "Specifically, only 200 CD44+/CD24-/low/ESA+/lin- breast cancer cells, isolated from patient primary tumors, could regenerate and expand to form secondary tumors that also contained CSCs, in as little as 12 weeks in mice." (PMID 22934288, 2012). "Human breast cancer cell lines contain CD44+CD24–/lowESA+ cells that exhibit characteristic stem cell features like anchorage-independent growth at clonal densities, the ability to reconstruct the parental cell fractions, along with enhanced tumorigenicity in mice." (PMID 22901246, 2012). "CD44+CD24-/low breast cancer stem cells might help clinicians to determine the presence of LN metastases." (PMID 23046710, 2012). "We then determined whether Oct1 levels correlated with cancer–initiating cell frequency using CD24/44 as a measure of mammary tumor-initiating cells." (PMID 23144633, 2012). "Expression of CD44, CD24, and E-selectin ligands on human breast cancer cell lines." (PMID 22934288, 2012). "Furthermore MPCs lack expression of CD24, K5, K14, CD49f and E-cadherin, further reinforcing their signature of claudin-low breast cancers." (PMID 22514728, 2012). "In particular, in a human breast carcinoma model originated from bone marrow micrometastases of a breast cancer patient, we have recently shown that the s.c growth of CD24+ and CD24− sorted breast cancer cell subpopulations and their single-cell clones resulted in similar take and growth rates." (PMID 21317983, 2011). "In the current studies, we utilized CD236/CD44/CD24 for isolation of CIC of breast cancer cells based on previous studies showing that ESA+/CD44+/CD24−or low breast cancer cell subset from human breast cancer tissue and breast cancer cell lines is more tumorigenic and more stem-like behavior." (PMID 21935375, 2011). "Additionally, following a low dose of radiation an increase in stem-like cells in the irradiated breast cancer cell population was detected by flow cytometric analysis utilizing the CD44/CD24 criteria for CIC." (PMID 21935375, 2011). "Moreover, the CD44+/CD24- phenotype was found to correlate with the more aggressive basal-like subtype of breast cancer." (PMID 21957977, 2011). "In addition, CD44/CD24 has been applied as a criteria marker for determining the stem-like CIC among breast cancer cell lines treated with various factors to favor the growth of or transition to stem-like cells." (PMID 21935375, 2011). "Other studies have also demonstrated an association between BRCA1 hereditary breast cancer and the presence of CD44+/CD24- cells, whereas our study points to the relationship between BRCA1 and CSC marker CD44 in unselected breast cancer patients rather than only in hereditary breast cancer patients." (PMID 23508738, 2011). "Moreover, we identify a novel tumor promoting mechanism of these cells that is enhanced upon exposure to PGE2: the ability to secrete factors (such as IL-6) that are essential for the expansion of CD44+/CD24−/EpCAM+ breast cancer cells." (PMID 21957456, 2011). "Therefore, the subset of CD44+/CD24−/low/ESA+ has been recognized as being breast cancer initiating cells (CIC)." (PMID 21935375, 2011). "CD44+/CD24-/low breast cancer cells have tumour-initiating properties with stem cell-like features." (PMID 23508738, 2011). "This prompted several attempts to characterise CD44+CD24-/low cells in primary breast carcinomas." (PMID 22112299, 2011). "Furthermore, the prevalence of CD44+CD24- cells in breast cancer patients indicates a link between high numbers of stem-like cancer cells and metastasis." (PMID 21067584, 2010). "CD44+/CD24- have been identified as markers for human breast cancer stem cells." (PMID 21044318, 2010). "All 16 breast cancer cell lines were analyzed for the expression of EpCAM, CD24, and CD49f to determine whether the same four differentiation states present within human breast tissues were retained in cultured lines." (PMID 20964822, 2010).
breast cancer (continued). "It is therefore likely that CD24−/low/CD44+ cells in breast cancer cell lines may behave in a manner similar to TICs." (PMID 19997106, 2010). "Since our observation of increased SLUG expression in CD44+/CD24- cells originated from a cell line study, we first examined the gene expression array data available in NCBI GEO omnibus to correlate SLUG expression with CD44+/CD24- status of primary breast cancers." (PMID 20691079, 2010). "Interestingly, a subpopulation of CD44 high/CD24 low CSC-like disseminated breast cancer cells were found in pleural effusions." (PMID 24281178, 2010). "In this regard, one study confirmed a putative stem cell phenotype in disseminated tumor cells (DTCs), and another study showed that the majority of early DTCs detected in the bone marrow of breast cancer patients with a CD44+/CD24- phenotype correlated with a higher prevalence of bone metastases." (PMID 19589136, 2009). "Due to the well-characterized dominant effect of CD44 on cell behavior and the fact that previous work has compared CD44dim/neg to CD44pos cells, the regulation of CD24 and its specific role in breast cancer cell behavior is largely unknown." (PMID 19906290, 2009). "At least one study has confirmed a putative stem cell phenotype in DTCs, and another study has shown that the majority of early DTCs detected in the BM of breast cancer patients with a CD44+/CD24- phenotype correlated with a higher prevalence of bone metastases." (PMID 19664291, 2009). "Basal-B lines were characterized by markers associated with aggressive tumor features, including PLAT (plasminogen activator) and TGFB1, as well as marker phenotypes associated with normal breast and breast cancer progenitor/stem cells (MUC−/CALLA+; CD44+/CD24−/low; and ITGB3(CD61)+)." (PMID 19582160, 2009). "In MDA-MB-231 cells, PROCR and ESA, instead of the widely used breast cancer stem cell markers CD44+/CD24-/low and ALDH, could be used to highly enrich cancer stem/progenitor cell populations which exhibited the ability to self renew and divide asymmetrically." (PMID 20027313, 2009). "CD24 expression was dynamically regulated in vitro in all evaluated breast cancer cell lines." (PMID 19906290, 2009). "We examined the impact of CD24 cross-linking on human breast cancer cell line MCF-7." (PMID 18433506, 2008). "One tumor had distinct features of EMT and gave rise to cell lines that contained a distinct CD44+/CD24-/low population that may correlate with human breast cancer stem cells." (PMID 18394172, 2008). "CD24 is important for progression, migration, and metastasis of human breast cancer." (PMID 18433506, 2008). "For this reason it is suggested that CD24 may play an important role in the progression and metastasis of human breast cancer." (PMID 18433506, 2008). "Hence, similar to the case in primary tumors, these tumorigenic breast cancer stem-like cells are enriched 100-fold in the CD44+/CD24-/low/ESA+ fraction across multiple cell lines." (PMID 18366788, 2008). "Breast cancer cells with a CD44+/CD24- phenotype have been suggested to have tumor-initiating properties with stem cell-like and invasive features, although it is unclear whether their presence within a tumor has clinical implications." (PMID 18559090, 2008). "Recently, CD24 was recommended as a prognostic indicator of poor patient survival in breast cancer." (PMID 18433506, 2008). "Metastatic tumor cells may have a more stem cell-like phenotype, as indicated by enrichment of the CD44+/CD24- phenotype in bone marrow micrometastasis of breast cancer patients." (PMID 18559090, 2008). "Given the reported similarity between murine breast and prostate stem cells and the recent identification of a CD44+CD24− subpopulation of breast cancer cells that have an increased tumorigenic capacity, we sought to identify and characterise CD44+CD24− cells in human prostate cell lines." (PMID 18268494, 2008).